ZEB1 (zinc finger E-box binding homeobox 1)
Diseases named in the same sentence as ZEB1 in open-access papers (continued):
Sharing a sentence is not in itself a finding about the gene and the disease.
tumor (continued). "Overall, our study provides a mechanism for the accumulation of myofibroblastic stroma in CMS4 tumours, pointing a spotlight on the miR‐200/ZEB1 axis in fibroblasts, and its regulation by tumour cell‐derived EVs." (PMID 35595718, 2022). "The findings presented here support a model in which ZEB1 activates a transcriptional program that coordinates collagen deposition and attachment to facilitate tumor progression." (PMID 34874914, 2022). "Overexpression of ZEB-AS1 promoted tumor development in prostate cancer by epigenetically upregulating zinc finger homeodomain enhancer-binding protein (ZEB1) expression, further activating the downstream target gene of ZEB1." (PMID 35030969, 2022). "By targeting epithelial gene promoters, ZEB1 is a dominant regulator of tumor cells and other cell types essential to tumor progression." (PMID 35454770, 2022). "ZEB1 orchestrates the transcription of genes in the control of several key developmental processes and tumor metastasis via the epithelial-to-mesenchymal transition (EMT)." (PMID 35454770, 2022). "The expression of ZEB1 in tumor tissues was lower than that in adjacent normal tissues, and the high expression of ZEB1 will promote longer OS and DFS (OS: P = 0.001; DFS: P = 0.038)." (PMID 35232428, 2022). "Mechanistically, we showed that Zeb1 regulates glucose uptake and the level of lactate, which is a metabolite that enhances tumor growth and induces an immunosuppressive TME." (PMID 35246504, 2022). "We recorded weekly changes in the tumor volume in nude mice, which revealed that the growth rate and size of tumors in the group of mice transfected with Sh-circ-ZEB1 were lower than those in the other group." (PMID 35277182, 2022). "Subsequently, we examined the protein levels of EMT markers and GSK-3β/β-catenin/ZEB1 pathway in nude mice tumor tissue." (PMID 36386155, 2022). "In this study, we proposed a mechanism by which hypoxia-induced Zeb1 potentiates the protumoral function of M2-like TAMs through promotion of lactate secretion to drive the formation of a tumor-supportive TME." (PMID 35246504, 2022). "The reported cadherin switch, and expression of EMT-associated transcription factors TWIST-1, ZEB-1, and HIF-1α were highly indicative for EMT events in the tumor, possibly explaining the metastatic behavior." (PMID 35215208, 2022). "Overall, ZEB1 is regulated by diverse signaling pathways at the transcriptional level, which in many cases are context- or tumor-specific." (PMID 35454770, 2022). "ZEB1 was overexpressed particularly in tumor cells at the invasive front and its knock-down promoted an epithelioid phenotype in CRC." (PMID 35565409, 2022). "ZEB1 modulates epithelial cell adhesion, and modulation of this adhesion is a key step for tumor cell invasion and metastasis 32,33." (PMID 35342335, 2022). "Instead, OCT4+ZEB1+β-catenin+ tumour cell expression showed shorter OS when combined with snail+vimentin+ tumour cell expression." (PMID 36358805, 2022). "Categorical univariate Cox regression showed that ZEB1+snail+ tumour cells and snail+CD44+ tumour cells were associated with longer OS and 5-year survival." (PMID 36358805, 2022). "TGF-β activates ZEB1 transcription by upregulating pSmad2 expression to provoke the mesenchymal state in multiple tumor types." (PMID 35454770, 2022). "As one of the transcription factors for EMT in tumor cells, ZEB1 down-regulates the transcription of E-cadherin in the nucleus as well as up-regulates the transcription of mesenchymal marker proteins, thereby promoting tumor metastasis." (PMID 35589690, 2022). "The results demonstrated that hypoxia stimulated Zeb1 expression at both the mRNA and protein levels in PyMT tumor cells, whereas this effect was strongly attenuated in PyMT;Zeb1cKO cells." (PMID 35246504, 2022). "The expression of ZEB1/2 in epithelial cells causes an EMT and mesenchymal phenotype in tumor stem cells, which promotes invasion, metastatic dissemination, and a dedifferentiated state." (PMID 36076302, 2022).
tumor (continued). "Although the number of analyzed cases is limited, these results emphasize the difficulty particularly for genes like ZEB1 whose expression in tumor cells is limited to a few scattered cells." (PMID 36119118, 2022). "ZEB1 is a key repressive transcription factor in EMT that induces PD-L1 expression in the tumor microenvironment, leading to immune suppression." (PMID 35326747, 2022). "In the present study, we have shown that ZEB1 promotes tumor cell dissemination by enhancing tumor cell adherence to collagen fibers and remodels the tumor microenvironment by increasing collagen deposition." (PMID 34874914, 2022). "Comparative analysis of PCR results indicated that Skip N2 tumor tissues had increased E-Cadherin/Vimentin ratio and ZEB1 mRNA expression, and significantly decreased levels of SLUG." (PMID 35201505, 2022). "By searching UALCAN database, we examined the expressions of MAPKAPK5-AS1, miR-429 and ZEB1 in HCC tumor tissues and adjacent normal tissues." (PMID 35468721, 2022). "ZEB1-mediating upregulation of various inflammatory cytokines is contributing to tumor formation and growth." (PMID 35454770, 2022). "ZEB1 is expressed in a subpopulation of cancer cells and affects their invasion and interactions with the tumor microenvironment, including immune cells that conduct surveillance." (PMID 35454770, 2022). "In patients with clinical stage I–III BC, miR-448 expression decreased with an increase in tumor stage, which was negatively correlated with ZEB1 expression." (PMID 35905576, 2022). "In vitro experiments using BLCA cell lines have shown that PI3K/Akt targets GSK-3β to regulate ZEB1 transcription and promote tumor invasion." (PMID 36061188, 2022). "Disruption in the function of key feedback loops can result in various undesirable consequences, such as ZEB1-mediated tumor progression." (PMID 35454770, 2022). "Recently, another study demonstrated that DNAJB9 blocked the tumor metastasis by enhancing Fbxo45-involved degradation of ZEB1 in TNBC cells." (PMID 35279684, 2022). "ZEB1 binding to the CDH1 promoter caused the recruitment of the CtBP to ZEB1’s CID, which ultimately suppresses CDH1 transcription and promotes tumor progression and metastasis." (PMID 35454770, 2022). "Most primary tumor cells maintained the expression of the epithelial markers EpCAM and ERα in our xenograft model while expressing ZEB1 and vimentin." (PMID 35440541, 2022). "The results showed that MAPKAPK5-AS1 and ZEB1 expressions were significantly upregulated in tumor samples, and miR-429 expression was downregulated." (PMID 35468721, 2022). "HIF1α was identified as a transcription factor of numerous genes related to the EMT, stem-like properties and metastasis of tumor cells, including Twist1, ZEB1 and ZEB223,24,43." (PMID 35941273, 2022). "ZEB1 expression promotes tumor progression by not only enhancing cell motility through the disassociation of polarized epithelial cells but also by reprogramming the surrounding tumor microenvironment to facilitate migration and invasion." (PMID 35454770, 2022). "Given the importance of the epithelial-to-mesenchymal transition in tumor progression and the pivotal role of ZEB1 as a transcriptional repressor during this process, the regulation of ZEB1-targeted gene expression is an active area of investigation." (PMID 35454770, 2022). "Our results reveal that pharmacologic or genetic PRMT5 inhibition blocks the expression of SNAIL, TWIST, and ZEB1 and almost completely blocks metastases in aggressive in vivo tumor models." (PMID 35803962, 2022). "Consistently, our study showed that M protein of SARS-CoV-2 activated the NFκB pathway, which is responsible for the upregulation of EMT and tumor progression-related genes, such as Zeb1/2, Snail, Twist and HIF-1α, in MDA-MB-231 cells." (PMID 35747796, 2022).
tumor (continued). "Apart from this, ZEB1 regulates other target genes involved in tumor progression such as Lgl2, PATJ, HUGL2, and Crumbs3." (PMID 36250005, 2022). "ZEB1-mediated immune responses also contribute to inflammation in the tumor micromilieu via its direct regulatory effect on the expression of IL-6." (PMID 36402997, 2022). "Our in vivo studies also indicated that reduction in SENP1 expression upregulated GATA1 SUMOylation, and thus resulted in decreased expression of CSN5 and ZEB1 in the tumor microenvironment, which decelerated TNBC progression and metastasis." (PMID 35342335, 2022). "Using lipopolysaccharide application to induce local inflammation in the lungs enhances tumor cell migration through a Zeb1-dependent mechanism." (PMID 36402997, 2022). "For example, in the two crucial gene sets Zeb1 and EGFR, Zeb1 is identified as one of the key EMT genes, and its overexpression is linked to tumor metastasis." (PMID 35645615, 2022). "Transcriptional and translational regulations contribute to the overall effect of ZEB1 in tumor progression and metastasis." (PMID 35454770, 2022). "Overall, our findings uncover the critical role of ZEB1 in promoting tumor progression and identify a novel inhibitor Biochanin A to block the ZEB1/PD-L1 axis." (PMID 35242187, 2022). "Positive correlation was found between CD8+ immune cells and PD-L1+ tumour cells and between OCT4a+ tumour cells and ZEB1+SNAIL+ tumour cells." (PMID 36358805, 2022). "As a driver of epithelial-mesenchymal transition, ZEB1 contributed to tumor progression and metastasis and correlated to dismal clinical outcomes in cancer patients." (PMID 36123704, 2022). "ZEB1-mediated EMT also regulates critical tumor cell signaling pathways, such as the MAPK pathway in KRAS-mutant tumors." (PMID 35454770, 2022). "For instance, the EMT transcription factor Zeb1 is not only a key factor in lesion formation, invasion and significant metastasis, but also can affect the stemness and colonization ability of tumor cells, especially phenotypic/metabolic plasticity." (PMID 36148233, 2022). "We developed tumor spheroids for parental and resistant Y79 cells, and we observed high ZEB1 and cathepsin L expression in resistant spheroids using immunofluorescence." (PMID 36291907, 2022). "Altered expression of Zeb1 has been reported in many cancers including PCa, and elevated Zeb1 expression confers further malignant behaviors on the tumor cells." (PMID 37305018, 2022). "ZEB1 regulates the expression of paracrine signals such as hepatocyte growth factor (HGF) and interleukin 6 (IL-6) in tumor cells and CAFs, highlighting that the ZEB1–CTGF axis plays a key role in regulating the network between tumor cells and CAFs." (PMID 35159011, 2022). "Taken together, these findings suggest that ZEB1 increases tumor cell affinity to Col1 by increasing Itga1 expression." (PMID 34874914, 2022). "In this review paper, we outline the biological roles of ZEB1 in mediating tumor progression and metastasis and describe the ways in which protein modifications can regulate its molecular associations and function." (PMID 35454770, 2022). "The correlation between miR-448 and tumor metastasis, clinical staging, and ZEB1 expression was analyzed." (PMID 35905576, 2022). "As important proteins of MAPK signaling pathway, ERK1/2 can modulate the migration and EMT of tumor cells through regulating ZEB1, SOX2, etc.." (PMID 36229838, 2022). "EMT is activated by tumor microenvironmental TGFβ signal and EMT-inducing transcription factors, such as ZEB1/2, in tumor cells." (PMID 36552758, 2022). "The expression of miR-429 was significantly lower and the expression of ZEB1 was higher in grade 1 tumor tissues than those in normal tissues." (PMID 35468721, 2022). "Here, we report that the epithelial-mesenchymal transition–activating transcription factor ZEB1 increased type I collagen (Col1) secretion and enhanced tumor cell adherence to Col1." (PMID 34874914, 2022).
tumor (continued). "Vimentin expression is affected by the downregulation of ZEB1, in turn constraining tumor migration." (PMID 36547923, 2022). "Of note, the use of OXM and EPI in combination had greater effects to limit tumor volume and weight in Zeb1/231 xenografts." (PMID 35246504, 2022). "ZEB1 is a key factor for cell fate determination, tumor initiation, cancer cell plasticity, and metastatic dissemination." (PMID 35440541, 2022). "Downregulation of ZEB1 also affects the enhancement of apoptosis of cancer cells, followed by a reduction in tumor invasiveness and migration through the expression of Wnt5a and vimentin." (PMID 36402997, 2022). "For instance, lncRNA-UCA1 promotes EMT in bladder cancer through sequestering tumor suppressive miR-145 that targets ZEB1/2 and fascin homologue 1 (FSCN1), an actin-binding protein that regulate actin-based cellular protrusions and cellular motility." (PMID 36114510, 2022). "Given the critical role of ZEB1 in EMT transition in various tumor types and phenotype switch and drug resistance in melanoma, ZEB1-AS1 represents an attractive stratification biomarker and molecular target in melanoma." (PMID 35159386, 2022). "Loss of MUC2, HSPB8, and SCG2 completely disrupted the formation of tumor spheroids in cells expressing ZEB1." (PMID 35440541, 2022). "This interaction decreases miR-217 and increases ZEB1 gene expression, a direct target of miR-217 able to induce tumor progression, promoting EMT with the activation of stem cell traits, immune evasion, and epigenetic reprogramming." (PMID 33540611, 2021). "Previous studies have shown that ZEB1 can be modulated by multiple pathways to promote tumor cell invasion and metastasis, playing a vital part in tumorigenesis and progression." (PMID 33397428, 2021). "The levels of Snail, Slug, and ZEB1 are higher in tumor cells withmorphological signs of EMT (the ability to migrate and invade) than in cellswithout signs of EMT." (PMID 33959388, 2021). "Deletion of Zeb1 in KPPC mice led to a decreased rate of primary tumor growth but an insignificant difference in disease-free survival of these mice when compared to the KPPC mice." (PMID 33852841, 2021). "Chaffer and colleagues demonstrated that the promoter region of Zeb1 plays an important role in enabling plasticity in tumor cells." (PMID 34072345, 2021). "JAG1 expressed on endothelial cells in the tumour microenvironment activates Notch1 in adjacent BCSCs, resulting in ZEB1 induction and increased stemness." (PMID 34295896, 2021). "This functional interaction leads to tumor progression via targeting of ZEB1, a transcription factor that promotes tumor invasion and metastasis by inducing epithelial-mesenchymal transition (EMT)." (PMID 33540611, 2021). "In vivo, GRP tumor growth was faster and maintained the gene signature: ZEB1‐miR200c‐BMI1 axis; high expression of mesenchymal and stem cell‐related factors; and reduced expression of epithelial marker." (PMID 33764690, 2021). "Compared to the bulk of the tumor, tumor budding cells in PDAC are reported to express increased levels of the EMT-related transcription factors ZEB1 and ZEB2 and decreased expression of the cell-to-cell adhesion protein, E-cadherin." (PMID 33806316, 2021). "It is worth noting that the role of ZEB1 in tumor treatment resistance has also begun to be recognized." (PMID 33391437, 2021). "Expression of Zeb1 on tumor cells and density of infiltrating immune cells were quantitatively evaluated with multicolor IHC in 40 tumors from DPP-4i users, 40 tumors from propensity score–matched users, and 40 tumors from nonusers." (PMID 36860286, 2021). "Arguably, it is possible that we underestimated the extent of labeled tumor cells, especially considering a marker like ZEB1." (PMID 34680248, 2021). "Palbociclib led to suppression of ZEB1, indicating a shift to an epithelial phenotype, and AZD6244 led to an accumulation of ZEB1, indicating the presence of mesenchymal-like tumor cells." (PMID 34309585, 2021).
tumor (continued). "Recently, the five member miR-200 family (miR-141, -200a, -200b, -200c, and -429) and miR-205 have been identified as EMT-suppressive or ‘tumor-suppressive’ miRNAs directly targeting ZEB1 and ZEB2." (PMID 34638432, 2021). "Thus, it is possible that the clinical significance of high B3GALT5 expression in adjacent non-tumor part of the cancer tissues might be associated with higher ZEB1 expression and other important but unrevealed role of B3GALT5 in regulation of tumor microenvironment to facilitate tumor progression." (PMID 33413566, 2021). "In the cases of oral squamous cell carcinoma and pancreatic ductal adenocarcinoma, the alteration of E-cadherin expression is accompanied by a simultaneous increase in the levels of EMT transcription factors Zeb1 and Zeb2 within tumor buds." (PMID 34771695, 2021). "Snai2 was found to associate with the gender, histological variants, BRAF/RAS phenotype, and lymph node metastases, while Zeb1 was found to be associated significantly with the histological variants, BRAF phenotype, tumor size, and disease recurrences." (PMID 34575184, 2021). "miR-641 has been reported to be a tumor-suppressive miRNA by targeting various downstream genes, including ZEB1, HOXA9, MDM2, and YAP1." (PMID 34603448, 2021). "ZEB1 was expressed by tumor cells from a single case, in our studied cohort, where the tumor stroma indicated the presence of a positive nuclear staining for ZEB1." (PMID 34680248, 2021). "ZEB1 owes its pivotal role to the downregulation of E-cadherin and the regulation of further proteins involved in tumor progression, such as Crumbs3, HUGL2, and PATJ (Pals1-associated tight junction)." (PMID 34884646, 2021). "In this study, we found a synchronous abundance of Snail and Zeb1 transcripts in human cancer samples and an inverse abundance between tumor suppressive miR-34a and miR-200 to EMT inducers." (PMID 34502497, 2021). "In detail, USP39 inhibits ZEB1 degradation through its deubiquitination function to promote HCC progression and TRIM26 degrades ZEB1 via ubiquitination to exert tumor-suppressive functions." (PMID 33649471, 2021). "According to prior reports, ZEB1 promotes tumor invasion and metastasis by inducing EMT in many cancers." (PMID 34093825, 2021). "EGR1 can synergistically act with SNAIL on the promoter regions of MMP9 and ZEB1, thereby enhancing their transcription and initiating tumor cell invasion and metastasis." (PMID 33842351, 2021). "Induction of Zeb1 KO in LSC mouse models of MLL-AF9– and Meis1a/Hoxa9-driven AML accelerated disease progression, implying that Zeb1 acts as a tumor suppressor in AML LSCs." (PMID 33108352, 2021). "Using ex vivo cultures of human PCa slices, which preserve both tumor microenvironment and cancer cell heterogeneity, we observed that Ohmline can prevent Enza-induced Zeb1." (PMID 34204608, 2021). "In CC, PCAT6 promotes cell proliferation and metastasis in vitro, and tumor growth in vivo through the miR-543/ZEB1 axis." (PMID 34885209, 2021). "In conclusion, we demonstrate that Snail and Zeb1 expression, in terms of transcript abundance as well as protein expression, is coordinated via tumor suppressive miRs in human cancer." (PMID 34502497, 2021). "We recently reported that dysregulation of the calcium signal can induce the transcription factor Zeb1, a key determinant of cell plasticity during tumor progression." (PMID 34204608, 2021). "Ectopic expression of miR-199a-5p in MDA-MB-231 cells inhibited the expression of the EMT-related genes CDH1, ZEB1 and Twist, and elevated levels of miR-199a-5p-impaired cell motility, invasiveness and tumor growth in vivo." (PMID 33572395, 2021). "In iCCA, ZEB1 is expressed both in tumor and stroma, and plays a key role in the induction of EMT in tumor cells." (PMID 35111082, 2021).